REN (renin)
Diseases named in the same sentence as REN in open-access papers (continued):
Sharing a sentence is not in itself a finding about the gene and the disease.
Hypertension (continued). "Among the genetic reasons, angiotensin II enzyme, produced as a result of abnormal functioning of the renin–angiotensin system, is reported as the foremost cause of hypertension." (PMID 30875817, 2019). "Many researchers point to vitamin D3 deficiency as a factor in the pathogenesis of hypertension (vitamin D3 inhibits renin and endothelin synthesis and the proliferation of smooth muscle cells), MetS, and diabetes (development of insulin resistance)." (PMID 30634516, 2019). "Because upregulation of plasma renin concentration (PRC) leads to hypertension and organ damage in humans, it would be of great importance to understand the underlying signaling mechanisms that trigger renin synthesis, secretion, and recruitment." (PMID 31379575, 2019). "NO inhibition by L-NAME in pregnancy caused programmed hypertension in adult offspring, which was associated with increased mRNA of renin and ACE in offspring kidney." (PMID 30764498, 2019). "There are also a number of transgenic hypertensive rats such as those that have been encoded with the mouse renin gene, which results in hypertension." (PMID 31681017, 2019). "It is associated with arterial hypertension, low plasma levels of renin, the regulatory enzyme that cleaves the angiotensin precursor angiotensinogen, and often with low serum concentration of K+." (PMID 31615979, 2019). "Normotensive individuals with higher aldosterone levels have a higher risk for developing hypertension, an association that is driven by normotensives exhibiting a PA phenotype: renin suppression with increasingly inappropriate aldosterone secretion." (PMID 29439489, 2018). "Uric acid can cause hypertension by mediating pro inflammatory pathways in vascular smooth muscles, inhibition of endothelial nitric oxide and activation of the renin-angiotensin system." (PMID 29986666, 2018). "Liddle syndrome is genetic autosomal dominant form of low renin arterial hypertension caused by germline mutations in the SCNN1A, SCNN1B and SCNN1G genes, encoding, respectively, the α, β and γ subunits of the epithelial sodium channel ENaC." (PMID 29534496, 2018). "High renin models of hypertension are typically associated with both an increase in arterial tone and a rise in ROS production." (PMID 29472601, 2018). "Elevated plasma renin and/or angiotensin-converting enzyme activities, which are associated with hypertension, were observed in psoriasis patients." (PMID 30142208, 2018). "Although the mutation Cx40A96S causes a renin-dependent hypertension, as that observed with global deletion of Cx40, the endothelial Cx37 levels are normal in these mice." (PMID 29874791, 2018). "Renin activity and aldosterone testing are indeed used to diagnose secondary causes of hypertension." (PMID 30349060, 2018). "Diabetes and hypertension increased the risk of kidney failure whereas renin-angiotensin blockade and HDL decreased the risk." (PMID 28666418, 2017). "For example, renin is associated with hypertension in kidney and sodium ion transport process is associated with hypertension in kidney." (PMID 28790372, 2017). "This survey demonstrates that Italian physicians considered left ventricular hypertrophy frequently associated to CVD and that drugs inhibiting the renin-angiotensin system the most appropriate therapy to manage hypertension and hypertension-related CVD." (PMID 28515958, 2017). "HF diet induced hypertension and renal injury are associated with oxidative stress, activation of renin-angiotensin system, and dysregulated sodium transporters and circadian clock." (PMID 28368364, 2017). "The decrease in 1,25(OH)2D3 can cause elevated angiotensin II production via an increase in renin expression, which results in hypertension and cardiac hypertrophy." (PMID 28977159, 2017).
Hypertension (continued). "For instance, aldosterone has been implicated in the development of cardiac fibrosis in hypertension; renin overexpression in hypertensive rats leads to cardiac remodelling and diastolic dysfunction via a fibrosis-independent “titin-related” mechanism." (PMID 28707261, 2017). "Excess aldosterone levels can arise from dysregulation of the renin-angiotensin-aldosterone system and are implicated in the pathogenesis of hypertension, chronic kidney disease and heart failure." (PMID 28352088, 2017). "Hypertension caused by increased renin-angiotensin system activation is associated with elevated reactive oxygen species production." (PMID 28298457, 2017). "There are several human studies reported that increased circulatory levels of renin and angiotensin II associated with hypertension." (PMID 28348564, 2017). "The presence of hypertension is presumed to be due to subcapsular collection causing compression of renal parenchyma and resulting in excessive renin release." (PMID 28639460, 2017). "A significant role of Renin-angiotensin system (RAS) genetic variants in the pathogenesis of essential hypertension and cardiovascular diseases has been proved." (PMID 28828324, 2017). "The occurrence of CHD with advancing age, is partially attributed to hypertension caused by the renin-angiotensin system." (PMID 27584680, 2016). "Human cell line studies have demonstrated that p.R337C mutation leads to the low activity of HSD11B2 due to reduced enzyme stability and causes low-renin hypertension thus resulting in AME9." (PMID 29067160, 2016). "In contrast to this, the rs6693954 polymorphism showed higher plasma renin activity levels and was found to be associated with hypertension in the HyperPath cohort of Caucasian subjects." (PMID 26753721, 2016). "Reductions in plasma catecholamines and renin activity brought about by weight loss is associated with decreased sympathetic activity, and is likely to be a determining factor for controlling hypertension." (PMID 27812597, 2016). "Acute Page Kidney (APK) phenomenon is a rare cause of secondary hypertension, mediated by activation of renin-angiotensin-aldosterone system (RAAS)." (PMID 27725836, 2016). "Overweight/obesity can increase the risk of hypertension by activating the sympathetic nervous system and renin-angiotensin system, inducing insulin resistance, and impairing endothelial function." (PMID 27322299, 2016). "ENPEP, as part of the renin-angiotensin system, has been shown to control blood pressure, and hypertension is a known risk factor for AF." (PMID 25888893, 2015). "Up-regulated renin-angiotensin activity is associated with systemic hypertension, renal dysfunction, vascular damage and cardiac hypertrophy." (PMID 25970442, 2015). "Contributions of renin in hypertension are associated with the presence of genetic variation in this gene." (PMID 26090220, 2015). "In this review, we analyze the molecular mechanisms of preeclampsia with a particular focus on the pathogenesis of the hypertension in preeclampsia and its association with the renin-angiotensin system." (PMID 26000015, 2015). "In weeks 5 to 8, hypertension is associated withincreases in tissue RAS components despite a fall in plasma renin activity andcirculating Ang II." (PMID 26270472, 2015). "It is characterized by hypertension with low plasma renin and elevated aldosterone and often associated with hypokalemia." (PMID 26124749, 2015). "To examine the underlying molecular alterations in association with hypertension, we examined several key components of the pulmonary renin-angiotensin system." (PMID 25971747, 2015). "PA is characterized by hypertension with elevated plasma aldosterone and low plasma renin levels, and often associated with hypokalemia." (PMID 26124749, 2015). "The mechanism by which vitamin D is believed to improve cardiac function and reduce the risk of hypertension is primarily via downregulating the renin-angiotensin-aldosterone system." (PMID 26246241, 2015).
Hypertension (continued). "In humans, GRK4 polymorphisms were shown to be associated with essential hypertension in Australia, BP regulation in young adults, low renin hypertension in Japan and impaired stress-induced Na excretion in normotensive black men." (PMID 25775155, 2015). "Hypertension occurs due to a relative hypoperfusion distal to the AVM causing increased renin secretion." (PMID 24716086, 2014). "Renin is an enzyme associated with hypertension, diabetes, and Alzheimer’s disease and is a rate-limiting enzyme in a cascade that starts with the cleavage of angiotensiogen and ends with the formation of angiotensin II." (PMID 24445304, 2014). "It is well recognized that RAS is associated with activation of the renin-angiotensin system which leads to systemic hypertension." (PMID 24708836, 2014). "Hypertension is a major risk factor for stroke, coronary events, heart and renal failure, and the renin-angiotensin system (RAS) plays a major role in its pathogenesis." (PMID 25009501, 2014). "Uric acid is associated with hypertension and increased renin–angiotensin system activity, although this relationship diminishes after chronic exposure to high levels." (PMID 25501427, 2014). "Hypertension in some patients is due to a dysfunction of RAS such as abnormal secretion of renin, causing increased blood angiotensin I levels." (PMID 24498151, 2014). "Increased production of renin from the affected kidneys causes blood pressure elevation, leading to the development of renin-mediated hypertension." (PMID 25177679, 2014). "Many clinical studies reported a specific ability of renin–angiotensin system (RAS) blockers in causing regression of hypertension-induced left ventricular hypertrophy." (PMID 25352832, 2014). "Metabolic syndrome (Mets), including diabetes and hypertension, increases the risk of colorectal cancer via the induction of chronic inflammation, acceleration of oxidative stress, and activation of the renin-angiotensin system." (PMID 24959250, 2014). "In humans, several forms of hypertension are associated with increases in plasma Ang II levels, such as renovascular hypertension and hypertension due to renin secreting tumors." (PMID 25400581, 2014). "Among pathophysiological disorders associated with Mets, in particular hypertension, activation of the renin-angiotensin system is considered to be critical in the early events of colorectal carcinogenesis." (PMID 24959250, 2014). "Reninomas are an uncommon but well-described cause of renin-mediated hypertension with about 100 reported cases to date." (PMID 25177679, 2014). "Juxtaglomerular cell tumors, also termed reninoma, are tumors of the renal juxtaglomerular cell apparatus, which causes hypertension and hypokalemia due to the hypersecretion of renin." (PMID 25364414, 2014). "Because of the association of long-standing severe hypertension and hypokalemia, our further work-up focused on the causes of renin-mediated hypertension." (PMID 25177679, 2014). "ROS are important in the pathogenesis of hypertension and the increase in ROS production and blood pressure, caused by stimulation of the renin-angiotensin-aldosterone system, is well known." (PMID 23985827, 2013). "This was associated with hypertension-related renin-angiotensin system activation and subsequent induction of oxidative stress and inflammation, suggesting that hypertension plays a critical role in the early stages of CRC." (PMID 23860206, 2013). "The juxtaglomerular cell tumor (JGCT) is a rare renal tumor characterized by excessive renin secretion causing intractable hypertension and hypokalemia." (PMID 23607027, 2013). "First, the typical variant, accounting for the majority, presents elevated plasma renin activity and secondary hyperaldosteronism causing hypokalemia and hypertension." (PMID 23607027, 2013). "Dysfunction of brain renin-angiotensin system (RAS) components is implicated in the development of hypertension." (PMID 23691105, 2013).
Hypertension (continued). "Hypertension was reversed and renin was suppressed by returning chow-fed vitamin D-deficient mice to vitamin D-sufficient chow diet for 6 weeks." (PMID 23349943, 2013). "Disruption of the D3R gene in mice (D3R−/−) caused renin-dependent hypertension that was associated with decreased ability to excrete an acute intravenous and chronic dietary salt load." (PMID 23985827, 2013). "Hypertension caused by activation of the renin-angiotensin system in diabetes mellitus plays an important role in the development of cardiac dysfunction in T2DM." (PMID 23446214, 2013). "The presence of abdominal fat increases sympathetic nervous system activity stimulating activation of the kidney renin-angiotensin system and causing peripheral vasoconstriction and hypertension." (PMID 22830026, 2012). "In the investigation of secondary causes of hypertension, plasma aldosterone-to-plasma renin activity ratio was elevated on two separate occasions, and primary hyperaldosteronism was confirmed by saline infusion test." (PMID 23110780, 2012). "Hypertension was shown to be a risk factor for RAS as well as a possible clinical manifestation of the activated renin angiotensin system secondary to RAS." (PMID 24757598, 2012). "PHPT is reported to be associated with hypertension, disturbances in the renin-angiotensin-aldosterone system, cardiac arrhythmias as well as structural and functional alterations in the vascular wall." (PMID 21403888, 2011). "This was accomplished by a large effort on the part of the Department of Family Medicine, in concert with a Hypertension Clinic using stimulated plasma renin levels to detect causes of secondary hypertension." (PMID 21532778, 2010). "Surgically correctable forms of primary aldosteronism are characterized by unilateral aldosterone hypersecretion and renin suppression, associated with varying degrees of hypertension and hypokalemia." (PMID 20482833, 2010). "In PPARα-deficient THM animals this hypertension is totally abolished, and this is accompanied by a reduction in plasma renin and by a normalization of serum aldosterone." (PMID 20613959, 2010). "Once rare causes of hypertension have been excluded, measuring the levels of plasma renin and aldosterone will identify the cause in most cases, for purposes of medical therapy." (PMID 21532778, 2010). "Clinical studies have shown primary aldosteronism or a decrease in renin to aldosterone ratio to be a significant cause of hypertension." (PMID 22043205, 2010). "Once those rare causes of hypertension are eliminated, the remainder are to be found in the renin-angiotensin-aldosterone axis, or in abnormalities of the renal tubular sodium channel." (PMID 21532778, 2010). "Aldosterone hypersecretion therefore increases exchangeable sodium, suppresses renin, increases the aldosterone to renin ratio, causes hypertension, and induces hypokalemia." (PMID 20482833, 2010). "We refer to recent reviews on the genetics of the renin–angiotensin–aldosterone system, G-proteins, adducin, and oxidative stress in hypertension, but will discuss the association of the aldosterone synthase gene (CYP11B2) with hypertension as an exemplar." (PMID 20035862, 2010). "Overactivation of the renin-angiotensin system constitutes an important contributor to the vascular remodelling associated with the onset of hypertension in SHR." (PMID 20592755, 2010). "An increased expression of renin and Ang II has been known to cause an increase in blood pressure or hypertension in humans." (PMID 19436702, 2009). "A familial aggregation study demonstrated that low renin hypertension was associated with the alpha-adducin G460W polymorphism." (PMID 19274077, 2009). "An amino acid polymorphism showing Lys173 rather than Arg173 in CYP11B2 gene has been associated with low-renin hypertension in Japanese populations." (PMID 19243623, 2009).
Hypertension (continued). "Hypertension is caused by various factors and the predominant causes include an increase in cholesterol levels, incidence of diabetes, inconsistent modulation of renin and imbalanced sexual hormones." (PMID 19865517, 2009). "Although the association of hypertension and hypokalemia are often attributed to primary hyperaldosteronism, the normal levels of plasma renin activity and aldosterone are opposed in this diagnosis." (PMID 19829770, 2009). "Aldosterone has deleterious effects on the cardiovascular system and it is possible that patients with hypertension who have a high aldosterone: renin ratio are at particular risk of cardiovascular morbid events." (PMID 17490489, 2007). "The genes of the renin-angiotensin have been linked to and/or associated with hypertension in animal models and humans." (PMID 17641732, 2007). "Hyperaldosteronism is characterised by excessive excretion of aldosterone with concomitant suppression of renin associated with hypertension." (PMID 17490489, 2007). "First, gain of function mutations in β and γ ENaC subunits cause Liddle's syndrome, a well-known monogenic form of human hypertension associated with low renin activity and low plasma aldosterone level." (PMID 15661075, 2005). "There are other studies that have examined the association of the components of the renin-angiotensin system with gender-specific hypertension." (PMID 23674950, 2005). "We decided to screen for common variants in the ENaC βand γ subunits in patients with essential hypertension and to relate their occurrence to the activity of circulating renin-angiotensin-aldosterone system." (PMID 15661075, 2005). "There are several features that collectively make the genes encoding the beta (βENaC) and gamma (γENaC) subunits of the kidney tubular epithelial sodium channel as serious candidates for susceptibility genes of low-renin human essential hypertension." (PMID 15661075, 2005). "This case-control study was designed not only to determine the association of the AGT M235T gene variants with essential hypertension, but also its relationship to Plasma Renin Activity (PRA) in subjects attending the Health Clinic, Kuala Lumpur, Malaysia." (PMID 15811183, 2005). "This hypertension was associated with increased renin and a decrease in neuronal nitric oxide synthase in the juxtaglomerular apparatus." (PMID 15507132, 2004). "Observations involving the renin–angiotensin pathway in rat congenital ID include a greater number of individual maculae densa cells and altered signaling in renin–angiotensin pathways that are linked to hypertension risk." (PMID 40220077, 2026). "Emerging evidence suggests that vitamin D deficiency may contribute to the development of essential hypertension through mechanisms involving the renin-angiotensin-aldosterone system and vascular endothelial dysfunction." (PMID 42131657, 2026). "Although its causal role remains speculative and balanced accuracy is modest, secondary hypertension has also been linked to aggressive tumor biology in other malignancies, such as adrenal cancers, via activation of the renin–angiotensin–aldosterone system." (PMID 40564764, 2025). "DOX also upregulated hypertension-associated genes in the renin–angiotensin system and endothelin." (PMID 40722850, 2025). "Additionally, obesity is strongly associated with hypertension, driven by heightened sympathetic activity, renin–angiotensin–aldosterone system activation, and impaired natriuresis, all contributing to elevated blood pressure and cardiac strain." (PMID 40573074, 2025). "However, renin levels differ significantly between the two groups of patients and were associated with postoperative hypertension, results reported by our group in a previous study." (PMID 41010423, 2025).